IGF1 (insulin like growth factor 1)
Diseases named in the same sentence as IGF1 in open-access papers (continued):
Sharing a sentence is not in itself a finding about the gene and the disease.
breast cancer (continued). "As an extra control group, we also performed additional IGF1 genotyping on BRCA1-negative women belonging to the South Swedish BRCA1 families with available DNA, who did not have breast cancer at the time of mutation testing." (PMID 15756256, 2005). "Suppression of the secretion of prolactin, growth hormone and insulin-like growth factor 1 (IGF-1) might be important in the growth regulation and treatment of breast cancer." (PMID 9459155, 1998). "In this study, multiplex immunohistochemistry, drug testing of HR + /HER2- breast cancer organoids, single-cell sequencing, and primary cell coculture showed that the CDK4/6 inhibitor palbociclib promotes fibroblast senescence, thereby increasing IGF1 and FGF7 levels." (PMID 41986650, 2026). "Research has shown that the binding of insulin and IGF‐1 to the insulin receptor can activate the PI3K/AKT/mTORC signaling pathway, stimulating cell proliferation and the transcription of metabolic genes, which promotes the growth of cancer cells and prevents apoptosis in breast cancer cells." (PMID 40550558, 2025). "These discrepancies may be due to differences in study design and participant characteristics; therefore, further research is necessary to clarify the role of vitamin D in regulating IGF-1 levels in obese individuals and to explore the independent role of IGF-1 in breast cancer cell migration." (PMID 39339753, 2024). "Moreover, the interplay between PAPP-A and IGF1 may influence other pathways crucial for tumor progression, such as PI3K/AKT and MAPK/ERK signaling, further enhancing breast cancer cell proliferation, survival, and metastasis." (PMID 38623138, 2024). "However, in breast cancer, GH has been shown to enhance proliferation, survival, invasion and angiogenesis in cancer cells, independent of IGF1." (PMID 37373068, 2023). "IGF-1-mediated activation of PI3K/GSK/-catenin was investigated in order to study potential molecular processes that may contribute to the effect of obesity and impaired glucose tolerance on breast cancer development and progression." (PMID 37511200, 2023). "In addition, BRCA has also been described as a metabolic regulator through its complex interactions with insulin/IGF-1 signaling axis and as transcriptional repressor of the gene IGF1R, main key players in the pathogenesis of T2DM-related complications and in breast cancer onset and progression." (PMID 37510134, 2023). "Interestingly, although they were not identified as clinically significant in breast cancer, cBioPortal analyses revealed significantly decreased levels of IGF1 mRNA and elevated levels of SHBG mRNA in Black samples in both BRCA-P and BRCA-C studies." (PMID 37345032, 2023). "The negative impact of CR on breast cancer growth may result from lowering bioavailable levels of IGF1." (PMID 37686596, 2023). "Our mediation analysis showed that childhood body size may have a negative effect on breast cancer indirectly via IGF-1." (PMID 35396499, 2022). "IGF-1 could also explain the negative correlation between BMI and early-onset breast cancer in premenopausal status of this study." (PMID 35277131, 2022). "Postmenopausal breast cancer patients (stages 0–III) who had completed anticancer treatment and received an oral supplement of melatonin (3 mg/day for 4 months) did not significantly improve the levels of serum biomarkers (estradiol, IGF1, IGFBP-3) related to breast cancer." (PMID 35409137, 2022). "Moreover, no clinico–pathological parameter was predictive of IGF-1 expression in breast cancer tissue in young patients." (PMID 35366286, 2022). "Mechanistically, we demonstrate that reduced circulating IGF-1 and HDL cholesterol levels might contribute to the negative association between obesity and overall, as well as ER+ breast cancer development." (PMID 36558416, 2022).
breast cancer (continued). "Afadin is phosphorylated at serine 1718 by Akt, which is activated in response to insulin-like growth factor-1, or by oncogenic alterations in the phosphatase and tensin homolog–PI3K–Akt pathway, and translocated into the nucleus, disrupting the AJs and enhancing migration in breast cancers." (PMID 36030821, 2022). "Importantly for breast cancer, aromatase—the rate-limiting enzyme for estrogen biosynthesis—is stimulated in the adipose tissue by adipose-derived factors (IL-1β, IL-6, TNF-α, and prostaglandin (PG) E2) as well as liver-derived IGF-1." (PMID 34066392, 2021). "Besides, insulin-like growth factor binding protein 3 (IGFBP-3) could inhibit cell proliferation and promote cell apoptosis by regulating local IGF-1 concentration and the anti-apoptosis effect of IGFBP-3 can be inhibited in breast cancer cells." (PMID 35096970, 2021). "There are fewer data on biomarkers for women at elevated breast cancer risk; these results suggest that elevated levels of IGF-1 and IGFBP-3 may be similarly related to breast cancer risk on a relative scale irrespective of absolute baseline risk." (PMID 33092613, 2020). "Since IGF-1 level were reduced in NAFLD patients 32, it could partially explain why ET-associated NAFLD had no significant impact on breast cancer outcomes." (PMID 32489477, 2020). "However, further understanding of the IGF1/SNHG7 system, the mechanisms of SNHG7 functions, and the characterization of other IGF1-regulated lncRNAs clearly will impact our understanding of both basic and breast cancer biology." (PMID 32444795, 2020). "In this regard, a high IGF-1 gene expression signature mediating cancer proliferation and survival has been assessed in TNBC cells and primary TNBC specimens, hence suggesting a rationale for targeting the IGF-1/IGF-1R system in this highly aggressive breast cancer subtype." (PMID 32325700, 2020). "Physical activity in breast cancer survivors may be more effective at modifying serum IGF-1 levels in women who are not taking tamoxifen, on the insulin pathway may be more pronounced for obese or sedentary women." (PMID 33467265, 2020). "In addition, chemerin treatment reduced the nuclear levels of β-catenin in breast cancer cells either stimulated with or not treated with TGF-β or IGF-1." (PMID 32325994, 2020). "Additionally, independent potentiating effects of GH that are not mediated by IGF1 have been demonstrated on breast cancer cells." (PMID 33260481, 2020). "A meta-analysis of 21 case-control studies including 3,609 cases and 7,137 controls has found that high concentrations of IGF1 and IGFBP3 were associated with an increased risk of incident breast cancer among premenopausal women but not among postmenopausal women." (PMID 32974138, 2020). "Finally, our data provide a rationale for the use of PRMT1 inhibitors to concomitantly target IGF-1 and estrogen nongenomic pathways in ERα-positive breast cancer therapies." (PMID 30692633, 2019). "In vivo experiments have demonstrated that circulating levels of diet-induced IGF1 was correlated with tumor progression and EMT in a murine model of luminal breast cancer, and diet-induced obesity promoted tumor progression and EMT in murine models of breast cancer." (PMID 30366466, 2018). "The modulations of IGF-1 and adiponectin by EE are likely more related to gender since both factors were not significantly changed in either young female wild type or a spontaneous breast cancer mouse model (data not shown, manuscript under review)." (PMID 30036185, 2018). "This may, to some extent, account for the lack of clinical efficacy of IGF-1-targeting agents in breast cancer and even in other cancers such as lung cancer." (PMID 28046018, 2017). "However, so far a role of IGF‐1 in development of SPCs following diagnosis of prostate cancer, breast cancer, colorectal cancer, or lung cancer has not been analyzed." (PMID 27734632, 2016).
breast cancer (continued). "Indeed, the cross talk between ER pathways and growth factor receptor pathways (EGFR, IGF-1, and HER2) has been involved in cell proliferation, survival, and resistance to endocrine therapy (TAM) in breast cancer (Yager & Davidson 2006, Pietras & Marquez-Garban 2007, Chang 2011)." (PMID 27357940, 2016). "IGF-1 induces anterior gradient 2 (AGR2) in the breast cancer MCF7 cell line, through an estrogen response element and a leucine zipper transcription factor-binding site on the AGR2 promoter playing a key role in IGF-1-induced breast cancer cell proliferation and migration." (PMID 26225961, 2015). "There was no important link between IGF-1 levels and postmenopausal breast cancer." (PMID 25198347, 2014). "Also, insulin and IGF1 are able to stimulate ER transcriptional activity in breast cancer cells, even in the absence of estrogen." (PMID 23750285, 2013). "Lycopene also interferes indirectly with cell-cycle progression by inhibiting the IGF-1-induced phosphorylation of tyrosine residues within the insulin-1 receptor substrate (IRS-1) and by inhibiting the DNA binding of the AP-1 transcription factor in breast cancer cells." (PMID 23970935, 2013). "IGF-1 increases proliferation of ER positive and negative breast cancer cells." (PMID 22860018, 2012). "Finally, we used a MMTV-Wnt-1 syngeneic orthotopic transplant model to evaluate the effects of CR (with and without) infused IGF-1 on mammary tumor growth." (PMID 23342276, 2012). "Finally, we analyzed the effects of 30% CR, with and without IGF-1 infusion, on mammary tumor growth using a syngeneic orthotopic transplant mammary tumor model." (PMID 23342276, 2012). "Because cytostasis is not a terminal state, breast cancer cells treated in the presence of IGF-1 could potentially escape antiestrogen- and/or antiprogestin-induced cytostasis via genetic or epigenetic changes that lead to the development of resistance." (PMID 22429491, 2012). "It has been previously shown that both PI3K and MAPK pathways are activated by IGF-1 to promote cell survival, but to our knowledge, it has never been shown that IGF-1 activates MMPs in a breast cancer cell line and that this, in part, functions via the PI3K and MAPK pathways." (PMID 21535875, 2011). "None of these adjustments altered the OR for IGF1 and breast cancer by more than 2% (data not shown) with the exception of adjustment for testosterone in postmenopausal women, which reduced the OR for an 80 percentile difference in IGF1 from 1·30 (95% CI 1·08–1·55) to 1·24 (1·04–1·49)." (PMID 20472501, 2010). "In summary, results from this large collaborative study support previous evidence that specific genetic variants in IGF1 and IGFBP3 genes significantly influence circulating levels of IGF-I and IGFBP-3, respectively, but have no measurable effect on breast cancer risk." (PMID 18596909, 2008). "The breakout group emphasized that nonsteroidal and nonpituitary hormones such as insulin-like growth factor 1 (IGF-1) and insulin may play a role in the etiology and progression of breast cancer." (PMID 17805427, 2007). "We have recently reported using RT-PCR that IGF-1 is lower in breast cancer tissue than in adjacent non-cancerous breast tissue (ANCT) thus supporting the paracrine hypothesis." (PMID 16725048, 2006). "Furthermore, the low expression levels of ADIPOQ (HR = 0.416, p < 0.01), IGF1 (HR = 0.458, p < 0.05), LEP (HR = 0.527, p < 0.05), NR3C1 (HR = 0.457, p < 0.05), and PPARG (HR = 0.491, p < 0.05) were notably related to the poorer BCSS of breast cancer patients with tumor pathological stages III–IV." (PMID 35317079, 2022). "MCF-7 breast cancer cells treated with exogenous IGFBP-3 showed increased apoptosis and this effect could be reversed by the use of non-IGFBP-binding IGF-1analog but not IGF-1 strongly indicating that IGFBP-3 induced apoptosis by sequestering IGF-1 from the receptor." (PMID 32478064, 2020).
breast cancer (continued). "Moreover, in vitro studies demonstrated that neurotrophic factors secreted by reactive astrocytes such as IL-6, transforming growth factor-β (TGF-β), insulin-like growth factor-1 (IGF-1), and chemokine ligand 12a (CXCL12a) may contribute to the development of brain metastasis from breast cancer." (PMID 31623643, 2019). "Nonetheless, our findings indicate that GPER and the IGF1/IGF1R axis are co-expressed in human breast tumors, suggesting that targeting IGF1R/GPER cross-talk might be useful in halting the angiogenesis process, particularly in a subset of breast cancer patients devoid of the classic ER." (PMID 29212519, 2017). "In breast cancer, the role of miR-126 in tumor metastasis may be related to the negative regulation of insulin receptor substrate-1 expression and it inhibits endothelial cell recruitment and angiogenesis through the negative regulation of IGFBP2/IGF1/IGF1R and GAS6/ MERTK signaling pathways." (PMID 24350576, 2013). "To characterize the effects of CR (with and without IGF-1 infusion) in the microenvironment in which mammary tumors arise in mice, we ran Insulin-PCR Super arrays (SABiosciences, Frederick, MD) using mRNA extracted from the mammary fat pads of control, 30% CR, and 30% CR + IGF-1 mice." (PMID 23342276, 2012). "In both normal and neoplastic cells IGF-1 regulates cell proliferation, mitogenesis and apoptosis and high IGF-1 levels have been associated with approximately twice the risk of developing premenopausal breast cancer and with a non-significant two fold increased risk of colorectal cancer." (PMID 21599947, 2011). "As an additional control group, we also performed IGF1 genotyping on 86 women with available DNA from the South Swedish BRCA1 mutation families who did not carry the mutation in their respective families and who did not have breast cancer at the time of testing." (PMID 15756256, 2005). "The absence of the IGF1 19-repeat allele may be a new biomarker of increased OC- and pregnancy-associated breast cancer, especially among BRCA mutation carriers where early-onset breast cancer is common." (PMID 15756256, 2005). "The fact that IR is not enriched in the CSC population, and that IGF-1 and IGF-2 are more effective regulators of CSC function than insulin, supports a dominant role for the IGF-1R in regulating breast cancer stemness." (PMID 36556357, 2022). "Nevertheless, brain metastatic disease has not been specifically investigated in IGF1‐targeting clinical trials, although inhibition of IGF1R has been shown to reduce breast cancer brain metastasis development in experimental models." (PMID 32534480, 2020). "FMD led to decreased blood glucose, serum IGF-1, leptin, and C-peptide levels as opposed to increased circulating ketone bodies in all patients with HR+/HER2—breast cancer." (PMID 33271979, 2020). "Given that MCF‐7 is a type of breast cancer cells expressing ERα but without expression of HER2 41, the cross‐talk mediating the acquired endocrine resistance was contributed to IGF‐1‐induced mTOR pathway." (PMID 28272775, 2017). "Among breast cancer-free control women, investigators found an inverted U-shaped association between BMI/WHR and IGF-1, consistent with the hypothesis that IGF-1 increases with body weight until a threshold is reached and activation of a negative feedback loop decreases hepatic IGF-1 production." (PMID 26352264, 2015). "There are abundant reports on the modulation of AGR2 expression in breast cancer; however, AGR2 promoter activation by IGF-1 has not been reported." (PMID 25956506, 2015). "In the present study, we found that Giα proteins not only regulated SDF1-mediated invasion of breast cancer (data not shown), but also controlled EGF-, bFGF-, IGF-1- and serum-induced MB231 invasion." (PMID 24521094, 2014). "Another possible explanation of why we did not see a further increase in IGF-1 serum levels beyond 6 months of age is that none of those Brca1f/f; MMTV-Cre mice at that age developed mammary tumors." (PMID 21888628, 2011).
breast cancer (continued). "Chemerin treatment more significantly inhibited cell invasion than cell viability in breast cancer cells in the presence or absence of TGF-β and IGF-1, which are growth factors that stimulate cancer cell invasion and are released from the bone matrix by osteolysis." (PMID 32325994, 2020). "Interactions between the IGF1 and BRCA1 signaling pathways are not restricted to breast cancer." (PMID 28706506, 2017). "Analysis of The Cancer Genome Atlas database showed that, unlike primary PIK3CA‐wild‐type and HER‐2+ breast carcinomas, PIK3CA‐mutant tumors display increased expression of AXIN2, HGF, STAT3, IGF‐1, and IGF‐2 mRNA and activation of AKT, IGF1‐MTOR, and WNT canonical signaling pathways." (PMID 28296140, 2017). "This study aims to elucidate whether variation in the IGF-1 pathway is predictive for pathologic response in early HER2 negative breast cancer (BC) patients, taking part in the phase III NEOZOTAC trial, randomizing between 6 cycles of neoadjuvant TAC chemotherapy with or without zoledronic acid." (PMID 26738606, 2016). "Although several reports demonstrated that IGF-1 can enhance MMP activity in both ER positive and ER negative breast cancer cells, we did not observe any increase in general MMP activity with either pII or YS1.2 cells treated with IGF-1 at similar dose range used in these studies." (PMID 22860018, 2012). "GPER, which is considered as a negative prognostic marker in breast cancer, has been shown previously to be upregulated and/or activated by a plethora of stimuli classically involved in HIF-1 pathway, including hypoxia, EGF, IGF1, insulin and the metals copper and zinc." (PMID 29212519, 2017).